CA9 (carbonic anhydrase 9)
Diseases named in the same sentence as CA9 in open-access papers (continued):
Sharing a sentence is not in itself a finding about the gene and the disease.
urothelial cell carcinoma (3 papers, 2013 to 2025). "The current study explored the effect of CA9 gene polymorphisms on the susceptibility of developing urothelial cell carcinoma (UCC) and the clinicopathological status." (PMID 24349364, 2013). "Distribution frequency of the clinical status and CA9 rs1048638 genotype frequencies in 221 patients with urothelial cell carcinoma." (PMID 24349364, 2013). "Distribution frequency of CA9 genotypes in 221 controls and 221 patients with urothelial cell carcinoma." (PMID 24349364, 2013). "Distribution frequency of the clinical status and CA9 rs1048638 genotype frequencies in 221 patients with urothelial cell carcinoma with non-smoker and smoker." (PMID 24349364, 2013).
abdominal aortic aneurysm (2 papers, 2022 to 2023). Enlargement and ballooning of the vessel that supplies arterial blood to the abdomen, pelvis and legs. "To evaluate a possible CA IX function in AAA formation, we performed an in silico analysis of abdominal aortic aneurysms to correlate CA9 gene with genes related to AAA formation." (PMID 35055064, 2022).
aseptic meningitis (2 papers, 2013 to 2014). Inflammation of the membranes surrounding the brain and spinal cord without a bacterial pathogen. "CA9 is one of the enteroviruses which may be associated with aseptic meningitis." (PMID 23347781, 2013).
benign renal tumor (2 papers, 2018 to 2020). "The results show that 86% of ccRCC had a positive expression of MN/CA9 mRNA, and no patient with a benign renal tumor exhibited MN/CA9 expression." (PMID 33585225, 2020).
bone cancer (2 papers, 2016 to 2021). A primary or metastatic malignant neoplasm affecting the bone or articular cartilage. "Our results showed weak, diffuse CA9 staining in bone tumors from LFD mice, whereas an abundance of CA9 protein with its typical membrane localization was detected in tumors from HFD mice, a result further confirming a glycolytic phenotype of bone tumors under conditions of high marrow adiposity." (PMID 27588494, 2016).
disc degeneration (2 papers, 2024). "CA9 upregulation in specific clusters (clusters 2, 3, 6, and 7) aligns with responses to hypoxic and acidic environments, implicating its role in disc degeneration." (PMID 39351146, 2024). "This suggests that CA9’s expression might facilitate cellular adaptation to the hypoxic and acidic microenvironments during disc degeneration." (PMID 39351146, 2024). "Therefore, targeting CA9 and strategies to improve the cellular micro-environment may offer new directions for the treatment of disc degeneration." (PMID 39351146, 2024).
endometriosis (2 papers, 2019 to 2022). The growth of functional endometrial tissue in anatomic sites outside the uterine body. "Significant differences were encountered between endometriosis and EC in case of five analytes, of which all were increased: ALDH1A (p = 0.019), CA9 (p = 0.031), CD44 (p = 0.010), hepsin (p = 0.007), midkine (p < 0.001)." (PMID 31035965, 2019). "Concentration of seven analytes (ALDH1A, CA9, CD44, hepsin, midkine, TGM2, and kallikrein-6) differed in endometriosis samples as compared to control samples and levels of five markers (ALDH1A, CA9, CD44, hepsin, and midkine) were different between endometriosis and EC samples." (PMID 31035965, 2019).
fibrosarcoma (2 papers, 2015 to 2020). A malignant mesenchymal fibroblastic neoplasm affecting the soft tissue and bone. "The transmembrane enzyme carbonic anhydrase 9 (CA9) contributes to the acidification of the extracellular environment and is necessary for the formation of invadopodia in fibrosarcoma cells." (PMID 33050151, 2020).
gallbladder carcinoma (2 papers, 2020). "In general, primary gallbladder carcinoma consistently shows positive staining for CK7, EMA, and CEA, but is negative for CA9 and vimentin." (PMID 32347406, 2020).
hepatoblastoma (2 papers, 2023 to 2024). Hepatoblastoma (HB) is a malignant hepatic tumor and is the most common pediatric liver cancer. "Previously it has been shown that CA inhibitor SLC-0111/U-104 downregulates CA9 expression at both protein and transcript levels in hepatoblastoma cell lines." (PMID 38530845, 2024).
lactic acidosis (2 papers, 2008 to 2021). Metabolic acidosis characterized by the accumulation of lactate in the body. "Interestingly, induction of some hypoxia-induced genes (e.g. CA9, Stanniocalcin1) was abolished by simultaneous lactic acidosis, consistent with previous studies." (PMID 19057672, 2008).
liver cirrhosis (2 papers, 2015 to 2018). "Soluble CA9 levels did not correlate with cell death markers in the sera of patients, namely M30 (r = 0.247, p = 0.074) and M65 (r = 0.202, p = 0.106), which were shown to be a prognostic marker of liver cirrhosis." (PMID 30011326, 2018).
lung squamous cell carcinoma (2 papers, 2012). "By contrast, an increased expression of CA9 had a protective effect for operable squamous cell lung cancer that may illustrate possible differences in prognostic significance of a given gene in surgical and non-surgical series." (PMID 22848476, 2012).
pancreatitis (2 papers, 2005 to 2020). Inflammation of the pancreas. "Expression of CA9 in the normal pancreas was stronger in areas of pancreatitis close to invading tumours." (PMID 15558070, 2005).
prostate tumor (2 papers, 2015 to 2019). "To address this question, we analyzed the expression of hypoxia marker gene CA9 by immunohistochemistry (IHC) in two independent tissue microarrays (TMAs) with 38 and 78 prostate tumor and benign tissue samples, respectively." (PMID 30655535, 2019).
rectal adenocarcinoma (2 papers, 2023 to 2025). "This is among the first evidence that IR can induce CA9 expression also observed in rectal adenocarcinomas post-chemoRT." (PMID 41316439, 2025).
viral infection (2 papers, 2020 to 2024). "Our results together with reanalyses of several RNA-Seq data available in the public domain further validated that CA9 was significantly associated with EBV induced B-cell transformation, particularly during early phase of viral infection event (2–4 DPI)." (PMID 38530845, 2024).
Acidosis (1 paper, 2025). Abnormal acid accumulation or depletion of base. "This CO2 is converted into HCO3− and H+ by membrane-bound CA9 and CA12, contributing to acidosis." (PMID 41316439, 2025).
acute leukemia (1 paper, 2022). A clonal (malignant) hematopoietic disorder with an acute onset, affecting the bone marrow and the peripheral blood. "As a result, the CA9 tumor gene could act as a potential early marker for acute leukemia prognosis." (PMID 36415514, 2022).
alcoholic liver diseases (1 paper, 2018). A disorder caused by damage to the liver parenchyma due to alcohol consumption. "Similar to the HCC cohort patients with alcoholic liver disease had significantly higher levels of CA9 (median 750 pg/ml, 16–1921) as compared to patients with other etiologies (median 367 pg/ml, 11–1470) (p = 0.008)." (PMID 30011326, 2018). "However, patients with alcoholic liver disease had significantly higher levels of CA9 (median 457 pg/ml, range 19–5066) versus patients with other etiologies (median 331 pg/ml, range 10–5080) (p = 0.028)." (PMID 30011326, 2018). "Subgroup analysis yielded significantly higher CA9 levels in both cohorts (HCC and without HCC) in patients with alcoholic liver disease compared to other diseases." (PMID 30011326, 2018).
aneurysm (1 paper, 2022). Bulging or ballooning in an area of an artery secondary to arterial wall weakening. "Results obtained from in silico analysis of CA9 and aneurysm-associated genes suggest a role for CA IX in aneurysmal wall remodeling." (PMID 35055064, 2022).
B-cell lymphomas (1 paper, 2024). "Future studies should focus in identifying the role of CA9 in regulating EBV latent to lytic switch and potential use of CA inhibitors for lytic induction therapy against multiple EBV associated B-cell lymphomas." (PMID 38530845, 2024). "In sum, our results identify variable CA9 expression and its associated activity during primary infection and lytic cycle replication, which we propose could be exploited for the treatment of multiple EBV-associated B-cell lymphomas." (PMID 38530845, 2024). "Additionally, significant CA9 expressions were also observed in both EBV positive and high EBNA2 expressing EBV positive B-cell lymphoma lines as compared to EBV negative and low EBNA2 expressing EBV positive B-cell lymphoma lines in DepMap portal." (PMID 38530845, 2024).
celiac disease (1 paper, 2021). An autoimmune genetic disorder with an unknown pattern of inheritance that primarily affects the digestive tract. "CRISPR/Ca9 could be a breakthrough for providing a promising dietary treatment for celiac disease." (PMID 34681400, 2021).
coronary heart disease (1 paper, 2022). "CA9, CBS, CEBPG, HSPB1, SLC1A4, HSPB1 and TRIB3 are genes that we have screened for iron death in coronary heart disease samples." (PMID 35152560, 2022).
dental caries (1 paper, 2021). The decay of a tooth, in which it becomes softened, discolored, and/or porous. "Neither TLN1 nor CA9 genes have been implicated in dental caries before, however, their plausible roles in craniofacial morphogenesis and pH regulation could suggest that they may influence cariogenesis." (PMID 34311721, 2021).
diabetic nephropathy (1 paper, 2025). "Among these, CA9 exhibited the largest fold change within the transcriptional regulatory network of HIF1A, while PDK1 was most closely associated with diabetic nephropathy." (PMID 40417738, 2025). "However, the role of CA9 in diabetic nephropathy and the regulation of renal fibrosis remains unclear." (PMID 40417738, 2025). "In the present study, we elucidated the novel anti‐diabetic nephropathy mechanism of ZGP and YGP through PPARA and HIF1A transcriptional regulatory networks and their specific downstream genes CA9, PDK1, and PDK4." (PMID 40417738, 2025). "CA9 and PDK1, the downstream genes of HIF1A, and PDK4, the downstream gene of PPARA, were activated by both EZP and EYP, which showed the potential new targets of diabetic nephropathy." (PMID 40417738, 2025).
enteroviral infections (1 paper, 2013). "Coxsackievirus A9 (CA9) was one of the most prevalent serotype of enteroviral infections in Taiwan in 2011." (PMID 23347781, 2013).
esophageal varices (1 paper, 2018). Abnormally dilated veins of the esophagus. "Higher CA9 levels in cirrhotic patients correlated with portal hypertension and esophageal varices." (PMID 30011326, 2018). "Patients with diagnosed esophageal varices had significant higher levels of CA9 (median 667 pg/ml, 11–1921) than patients without varices (median 319 pg/ml, 23–1277) (p = 0.03)." (PMID 30011326, 2018). "Interestingly CA9 levels correlated with markers of portal hypertension (soluble CD163 and platelet count) and is significantly increased in patients with diagnosed esophageal varices supporting further investigations in cirrhotic patients and as a marker for portal hypertension." (PMID 30011326, 2018).
gastroesophageal reflux disease (1 paper, 2015). A chronic disorder characterized by reflux of the gastric and/or duodenal contents into the distal esophagus. "High CA9 expression may be related to the acidic environment in the gastroesophageal junction caused by gastroesophageal reflux disease." (PMID 26156831, 2015). "High CA9 expression may be related to the acidic environment caused by gastroesophageal reflux disease in the gastroesophageal junction and associated with tumorigenesis through BMI1, MCM4 and MCM7." (PMID 26156831, 2015). "High levels of CA9 in columnar cell metaplasia and other precancerous glandular lesions may protect glandular cell survival in the acidic environment induced by gastroesophageal reflux disease." (PMID 26156831, 2015).
HIV-1 infection (1 paper, 2022). The type species of lentivirus and the etiologic agent of acquired immunodeficiency syndrome (AIDS). "HIF-1α accumulation was consistent with the temporal induction of a gene set of hypoxia responsive genes (e.g., CA9, PFKFB4, and VEGF) in our transcriptome analysis and the idea that HIF-1α enhances HIV-1 infection by binding hypoxia-responsive elements (HRE) present at the 5′-LTR." (PMID 36298843, 2022).
ischemia (1 paper, 2021). A hypoperfusion of the BLOOD through an organ or tissue caused by a PATHOLOGIC CONSTRICTION or obstruction of its BLOOD VESSELS, or an absence of BLOOD CIRCULATION. "Learning more about the mechanisms responsible for the expression of hypoxia-inducible proteins such as VEGF-A and CA9 can further our understanding of (patho)physiological conditions such as development, ischemia, and the human tumor microenvironment." (PMID 33675747, 2021).
latent infection (1 paper, 2024). "We show that while CA9 expression is transcriptionally activated during latent infection model, lytic cycle replication restrains its expression." (PMID 38530845, 2024). "While during EBV latent infection elevated CA9 functions appears to be necessary for efficient B-cell transformation and survival of transformed B-lymphocytes, intermittent switch to lytic replication cycle blocks its activity." (PMID 38530845, 2024). "Elevated CA9 expression during EBV latent infection, prompted us to further investigate CA9 expression pattern during lytic cycle reactivation." (PMID 38530845, 2024). "Our results demonstrated that in contrast to EBV latent infection, lytic cycle reactivation by a combination of HDAC inhibitor sodium butyrate and protein kinase C inducer phorbol ester caused a significant decrease in CA9 expression." (PMID 38530845, 2024).
lipoma (1 paper, 2025). A benign, usually painless, well-circumscribed lipomatous tumor composed of adipose tissue. "The mRNA expression of CA9 was significantly upregulated only in the fifth passage compared to lipoma cells." (PMID 40646808, 2025). "CA9, a hypoxia-induced gene involved in tumor progression and metabolic adaptation, was significantly upregulated in the fifth passage compared to lipoma cells." (PMID 40646808, 2025).
portal hypertension (1 paper, 2018). Increased blood pressure in the portal venous system. "As CA9 is mainly expressed in the gastrointestinal tract, portal hypertension and associated comorbidities (e.g. hypertensive gastropathy) could be another source of high CA9 levels." (PMID 30011326, 2018). "The high CA9 levels are probably mainly associated with portal hypertension." (PMID 30011326, 2018). "As CA9 expression is limited to only a few normal tissues, mainly the epithelia of the gastrointestinal tract, an elevated level however, is a potential marker for liver disease." (PMID 30011326, 2018). "The CA9 levels did not significantly vary in patients with the indicated etiologies of liver disease (p = 0.403, p = 0.767 and p = 0.438, for HBV, HCV infection or NASH, respectively)." (PMID 30011326, 2018).
Pruritus (1 paper, 2013). Pruritus is an itch or a sensation that makes a person want to scratch. "Of the CA9-infected patients with skin rashes, distribution was mainly seen over the trunk, extremities, face (70%, 70%, and 61%, respectively), while hands and/or feet only 10%; 23% of patients with skin rashes had pruritus." (PMID 23347781, 2013).
Renal Angiomyoadenomatous Tumor (1 paper, 2025). A very rare, benign, encapsulated tumor that arises from the kidney. "Unlike CCPRCT or related renal angiomyoadenomatous tumors, ELOC-mutated RCC lacks prominent subnuclear vacuoles, and CCPRCT typically shows a “cup-shaped” CA9 staining pattern." (PMID 41357565, 2025).
renal fibrosis (1 paper, 2025). A final common manifestation of a wide variety of chronic kidney diseases characterized by glomerulosclerosis and tubulointerstitial fibrosis. "In this study, we found that ZGP, YGP, and its components activated the transcriptional regulatory networks of HIF1A, as well as the downstream genes PDK1 and CA9, which were closely associated with renal fibrosis and ECM degradation." (PMID 40417738, 2025). "ZGP and YGP mediated HIF1A networks and downstream genes of CA9 and PDK1 in TGFβ‐induced HK2 cells for improving renal fibrosis." (PMID 40417738, 2025).
rheumatoid arthritis (1 paper, 2024). A chronic, systemic autoimmune disorder characterized by inflammation in the synovial membranes and articular surfaces. "For instance, rheumatoid arthritis (RA) synovial fibroblasts upregulate CA9 up to 28-fold under hypoxia, a hallmark of RA." (PMID 39768175, 2024).
skin rashes (1 paper, 2013). "Sixty one percent of CA9-infected patients had skin rashes observed during physical examination." (PMID 23347781, 2013).
Thrombocytopenia (1 paper, 2024). A reduction in the number of circulating thrombocytes. "The treatment can also cause severe thrombocytopenia, possibly related to CA9–platelet interaction." (PMID 39768175, 2024).
thymic carcinoma (1 paper, 2019). Thymic carcinoma (TC) is a type of thymic epithelial neoplasm characterized by a high malignant potential. "CA9 is a well-known gene, and it could be a good therapeutic target for thymic carcinoma." (PMID 30863491, 2019).
thymoma (1 paper, 2019). A neoplasm arising from the epithelial cells of the thymus. "CA9 expression was undetectable in type A thymomas, and only 4/93 (4.3%) of low-risk thymoma expressed CA9, whereas 17/21 (81.0%) of TCs expressed CA9." (PMID 30863491, 2019). "Although the frequency of CA9 expression by high-risk thymoma, especially type B3 tumors, was higher compared with that of CA9 mRNA expression, the positivity of CA9 expression gradually increased according to histology, and CA9 expression data were generally consistent with its mRNA levels." (PMID 30863491, 2019). "For example, an analysis of tissue microarrays found that CA9 serves as a diagnostic marker that distinguishes TCs from type B3 thymomas, though the diagnostic specificity and sensitivity of CA9 was not higher compared with those of glucose transporter 1 (GLUT-1) or KIT." (PMID 30863491, 2019).
vascular occlusion (1 paper, 2006). "For stain area, only CA-9 and GLUT-1 increased following vascular occlusion." (PMID 16404365, 2006).